HP (haptoglobin)
Diseases named in the same sentence as HP in open-access papers (continued):
Sharing a sentence is not in itself a finding about the gene and the disease.
COVID-19 (31 papers, 2020 to 2026). A disease caused by infection with severe acute respiratory syndrome coronavirus 2. "Serum haptoglobin has been shown to be decreased in critical cases of COVID-19, potentially because of hemolytic anemias, with hemolysis initiated by SARS-CoV-2 infection of erythrocytes releasing hemoglobins." (PMID 41557029, 2026). "We found altered glycopeptide abundances among proteins important in COVID-19, including haptoglobin, transferrin and immunoglobulin A (IgA)." (PMID 37474612, 2024). "For instance, plasma levels of serumamyloid A protein, C-reactive protein, Alpha-1-acid glycoprotein 1,mannose-binding protein C, haptoglobin, and attractin were significantly elevatedin the COVID-19-related AVB group." (PMID 39076308, 2024). "Consistent with bands on the Coomassie stained gel, the level of haptoglobin was greater in COVID-19 samples compared to healthy but the 16 kDa haptoglobin band was missing in some samples." (PMID 36765106, 2023). "In our study, HP was upregulated in the colostrum of the COVID-19 group, coinciding with the mild clinical symptoms of these mothers." (PMID 37628421, 2023). "The white blood cell count and haptoglobin levels were significantly elevated in the COVID-19 positive group." (PMID 35215486, 2022). "Before COVID-19, T2DM was associated with a significant and very early increase in haptoglobin in patients younger than 20 years of age compared with non-T2DM patients, both in men and women." (PMID 35327501, 2022). "During COVID-19, T2DM was associated with a significant and very early increase in haptoglobin in patients younger than 20 years of age compared with non-T2DM patients, both in women (0.25 g/L vs 0.12 g/L) and men (0.14 g/L vs 0.02 g/L)." (PMID 35327501, 2022). "We observed a negative correlation of cfDNA with the ADAMTS13:VWF ratio, a marker associated with COVID-19 severity and severe AKI, along with a positive correlation with LDH, ferritin, and haptoglobin, suggesting a picture of a secondary TMA." (PMID 35497096, 2022). "Despite elevated LDH levels in 60/63 (95%) patients being compatible with haemolysis, available haptoglobin values from 22 patients across all COVID-19 stages were all normal or elevated." (PMID 33572417, 2021). "By applying OxoScan-MS to quantify 1,002 glycopeptide features in the plasma glycoproteomes from patients with COVID-19 and healthy controls, we found that severe COVID-19 induces differential glycosylation in IgA, haptoglobin, transferrin and other disease-relevant plasma glycoproteins." (PMID 37474612, 2024). "In pediatrics, COVID-19 liver injury was associated with mild haemolytic aneamia, elevated lactate dehydrogenase, elevated anti-liver-kidney-microsomal antibody (anti-LKM) and undetectable haptoglobin." (PMID 37185723, 2023). "Finally, we observed upregulation of markers of hemolysis (haptoglobin [Hb scavenger] and hemopexin [heme scavenger]), which have been reported to be heightened in COVID-19 infected human patients." (PMID 36614003, 2022). "The means of haptoglobin were even higher than before COVID-19 only in obese patients." (PMID 35327501, 2022). "In contrast, there is evidence for higher levels of hemopexin and haptoglobin in COVID-19 patients." (PMID 33925394, 2021). "Serum levels of iron and hepcidin are low in COVID-19 patients, whereas erythropoietin (EPO) and haptoglobin levels significantly decline in critical and deceased patients." (PMID 38555403, 2024). "We found that the plasma levels of HP, LTA4H, S100A9, SAA1, SAA2, and SERPINA3 were significantly elevated in more severe COVID-19 conditions, exhibiting good clinical predictive value and promising applications." (PMID 37197655, 2023). "In our study, the low serum zonulin levels in COVID-19 patients with a moderate clinical course can be explained by the conversion of pre-haptoglobin to haptoglobin in cases of non-severe inflammation." (PMID 36158380, 2022).
COVID-19 (continued). "When compared to controls, COVID-19 patients independently on their disease severity had lower plasma levels of ALB (by 42%) but significantly higher levels of AGP (by 2.4-fold), AAT (by 1.9-fold), CP (by 1.4-fold), HP (by 3.8-fold), and hs-CRP (by 52-fold)." (PMID 36514048, 2022). "When COVID-19 patients were segregated into subgroups, amongst the patients with a moderate disease, strong correlations were found between AAT and AGP (r = 0.91, p < 0.001), HP (r = 0.79, p < 0.01), hs-CRP (r = 0.72, p < 0.01), and CP (r = 0.89, p < 0.01)." (PMID 36514048, 2022). "Both, severe and mild COVID-19 in comparison to controls shared neutrophil-specific CD177 and HP expression among the most upregulated DEGs, as well as lymphocyte-associated genes such as ABLIM1, NELL2, RCAN3, RORC, BACH2, and KLRB1, among the downregulated genes." (PMID 33441124, 2021). "When compared to controls, COVID-19 patients had significantly lower concentrations of ADAMTS13 and albumin (ALB) but higher M30, M65, α1-acid glycoprotein (AGP), α1-antitrypsin (AAT), ceruloplasmin (CP), haptoglobin (HP), and high-sensitivity C-reactive protein (hs-CRP)." (PMID 36514048, 2022). "COVID-19 patients produced greater ORM-1, alpha-1-antitrypsin, and haptoglobin acute phase proteins compared to both COVID-19 negative and healthy control patients." (PMID 38786270, 2024). "Albeit without statistical significance, levels of AGP, HP, and CP also increased but A2MG decreased in COVID-19 severity-dependent manner." (PMID 36514048, 2022). "For instance, IL1B, NFKB1, NLRP3, PYCARD, and CASP1 are listed in the COVID-19 Disease Map, while there are molecules absent from it, including CCL3, 3L1, 4L2, CXCL1, 2, 3, 5, 16, TNFAIP6, C15orf48, TMEM176A/B, NFE2, PADI4, RAB20, ETS2, PHLDA2, FOLR3, and HP." (PMID 37719701, 2023). "EVs collected from the serum of both healthy controls and patients with COVID-19 were confirmed by transmission electron microscopy, and western blotting confirmed the expression of CD9, CD63, and flotillin-1, while calnexin and haptoglobin expressions were negative." (PMID 36451245, 2022).
breast cancer (30 papers, 1979 to 2025). A primary or metastatic malignant neoplasm involving the breast. "In other cancers, such as breast cancer, the upregulation of haptoglobin has been associated with increased tumor growth and metastasis." (PMID 37894372, 2023). "Regarding human haptoglobin (HP), it has been reported to be secreted upon neutrophil activation, contributing to breast cancer oncogenesis by modulating glycolytic activity." (PMID 39676870, 2024). "This study aims to evaluate disease-specific haptoglobin (DSHp)-β N-glycosylation as a potential biomarker for breast cancer diagnosis." (PMID 38575942, 2024). "In agreement with our results, increases in serum haptoglobin concentrations were observed in dogs with mammary tumors when compared to healthy controls, as well as in dogs with hemolymphatic, mesenchymal, and epithelial tumors." (PMID 32344524, 2020). "This corresponds to a case-control study investigating if it was possible to detect early stages of breast cancer by a serum panel of ten potential breast cancer markers, where haptoglobin was one of them." (PMID 31042781, 2019). "In attempt to reveal the potential biomarkers for breast cancer, the findings of differentially glycosylated haptoglobin and osteonectin in previous study have drawn our attention towards glycoproteins of secretome from the MCF-7 cancer cell line." (PMID 26167486, 2015). "Taking 4 of the markers (carcinoembryonic antigen (CEA), lactalbumin, alpha subunit and haptoglobin) serum concentrations of one or more were raised in 33% of patients with local disease and 81% of those with advanced breast cancer." (PMID 92331, 1979). "The higher efficacy of chitosan nanoparticles loaded with recombinant HP-NAP against breast cancer in mice could be due to the reason that chitosan nanoparticles act as adjuvants to the main immunotherapy protein." (PMID 36613542, 2022). "Moreover, especially haptoglobin but also fibrinogen beta were indicative of metastasis in a human triple-negative MDA-MB-231 breast cancer model." (PMID 35328392, 2022). "Main inclusion criteria were known diagnosis of breast cancer, presence of schistocytes and either low haptoglobin or cytopenia and absence of any causes of MAHA other than breast cancer, including gemcitabine- or bevacizumab-based treatment." (PMID 33468209, 2021). "Some of the modulated proteins found in the present study such as haptoglobin or S100A4 have been related to CMT or human breast cancer previously, while others such as kallikrein-1 and immunoglobulin gamma-heavy chains A and D are described here for the first time." (PMID 32344524, 2020). "It has previously been reported that haptoglobin is elevated in breast cancer and may be indicative of metastases." (PMID 29788918, 2018). "A small study found haptoglobin phenotypic polymorphism was associated with familial breast cancer, but no studies have reported on the relationship between SNPs in this gene and breast cancer risk." (PMID 28957356, 2017). "Further larger studies could investigate the relationship between major HP genotype/phenotype (HP1-1, HP1-2, and HP2-2) and breast cancer risk." (PMID 28957356, 2017). "The present data suggested that osteonectin and haptoglobin might have potential to be served as potential biomarkers for breast cancer." (PMID 25484625, 2014). "The poor prognosis of our Hp 2-2 breast cancer patients in our discovery set (n = 63) could be exerted via this haptoglobin function, since angiogenesis is well known to be involved tumor growth, proliferation, and metastasis." (PMID 19108738, 2008). "In contrast to our initial results, the haptoglobin phenotype was not identified as a predictor of recurrence free survival in high-risk primary breast cancer in our validation set." (PMID 19108738, 2008). "Thus, Haptoglobin probably is a biological prognostic marker for patients with breast cancer." (PMID 32232956, 2020).
breast cancer (continued). "This suggests that especially changes in haptoglobin, but also fibrinogen beta chain, thrombospondin-4 and transferrin receptor protein 1 is indicative of metastasis, at least in this breast cancer model, and should be further evaluated as general breast cancer biomarkers." (PMID 31042781, 2019). "In conclusion, although we initially found the haptoglobin phenotype to be a predictor of recurrence free survival in a limited number of high-risk primary breast cancer patients, this was not confirmed following validation by analysis of a similar, but six-fold larger sample set." (PMID 19108738, 2008). "Haptoglobin was several fold upregulated on the NGS, nanostring and MS analysis of mEHT-treated breast cancer and on the MS screen validated by PCR in the ischemic kidneys." (PMID 35328392, 2022). "Using transgenic mouse models that spontaneously develop mammary tumors mimicking human breast cancer, we previously found two markers, osteopontin (OPN) and haptoglobin, which completely distinguished mammary-tumor bearing mice from non-tumor mice." (PMID 23202969, 2012). "Even a combined analysis of a serum panel of potential breast cancer markers, consisting of osteopontin, haptoglobin, haptoglobin, CA153, CEA, CA-125, prolactin, CA19-9, α-fetoprotein, leptin and migration inhibitory factor, is unable to predict the presence of early-stage breast cancer." (PMID 33803633, 2021). "The haptoglobin phenotype has not been identified as a predictor of recurrence free survival in breast cancer thus far." (PMID 19108738, 2008). "For overall breast cancer risk, there was no gene with a P-value that deviated from the null distribution, but for ER-negative breast cancer risk analysis, there were several genes with P-values smaller than expected, including TP53INP2, HP, and DHODH." (PMID 28957356, 2017). "In addition, some of the modulated proteins found in the present study such as haptoglobin or S100A4 have been related to CMT or human breast cancer previously, which confirms the validity of our study design for CMT evaluation and the use of CMT as a model for breast cancer research." (PMID 32344524, 2020).
ovarian carcinoma (27 papers, 2004 to 2025). A malignant neoplasm originating from the surface ovarian epithelium. "Of the serum inflammatory markers in the AMORIS cohort, women with ovarian cancer who had elevated levels of haptoglobin (≥1.4 g/L) had a higher risk of dying from ovarian cancer compared to those with haptoglobin levels <1.4 g/L (HR = 2.09, 95% CI:1.38–3.16)." (PMID 31069161, 2019). "Cox proportional hazards regression analysis showed a positive association with risk of dying from ovarian cancer for those with higher levels of serum haptoglobin (≥1.4 g/L) compared to those with haptoglobin levels <1.4 g/L (HR = 2.09, 95% CI:1.38–3.16)." (PMID 31069161, 2019). "Strong association between abnormally fucosylated haptoglobin and α 1,3 fucosyltransferase activity has been demonstrated in the blood specimens of ovarian cancer patients." (PMID 15199385, 2004). "After a follow-up time of 20 years, 15% of the women with haptoglobin levels ≥1.4 g/L had survived ovarian cancer compared to 39% of the women with haptoglobin levels <1.4 g/L (log Rank P-value <0.001)." (PMID 31069161, 2019). "In a study by Mahyuddin and etal, they demonstrated the presence of haptoglobin in ovarian cyst fluid of benign, borderline and malignant epithelial ovarian cancer." (PMID 31315664, 2019). "Haptoglobin has also been indicated as a serum biomarker for ovarian cancer and small cell lung cancer." (PMID 31042781, 2019). "The median survival time for ovarian cancer was 1.3 years shorter when women had haptoglobin levels ≥1.4 g/L compared to women with haptoglobin levels <1.4 g/L." (PMID 31069161, 2019). "A reverse lectin ELISA based on AAL capture of fucosylated haptoglobin was recently used to differentiate patients with ovarian cancer from normal controls, showing the feasibility of this approach for other highly abundant glycoproteins such as haptoglobin." (PMID 28296934, 2017). "Wu and colleagues used a fucose specific lectin, Aleuria aurantia lectin (AAL) to characterise the fucosylation of haptoglobin in ovarian cancer and found increased levels of fucosylated haptoglobin in patient sera." (PMID 28248271, 2015). "Tissue detection of Haptoglobin and its fucosylated form, by histo-immunofluorescence in biopsies of ovarian cancer, also showed a correlation with ovarian cancer progression." (PMID 24576319, 2014). "Our list of peptides found in ovarian cancer specimens includes fragments derived from the proteins vitronectin, transketolase and haptoglobin." (PMID 24694173, 2014). "Many acute phase proteins such as haptoglobin and transthyretin have also been recently characterized as ovarian cancer biomarkers for early detection." (PMID 23251472, 2012). "Haptoglobin (Hp) has also been suggested as a biomarker for ovarian cancer but we observed elevated levels of Hp in all confounder models." (PMID 21589862, 2011). "One study, which accounted for 66 malignant ovarian tumors, 60 benign ovarian tumors, and 10 normal healthy women, found significantly higher levels of haptoglobin in early-stage disease than among healthy controls." (PMID 21577260, 2011). "As an acute phase reactant protein that originates mainly from the liver, haptoglobin has been shown to be expressed in some forms of ovarian cancer within the ascitic fluid and serum as reported in several studies." (PMID 21577260, 2011). "For example, haptoglobin was first shown to be elevated in the sera of women with ovarian cancer almost 40 years ago." (PMID 20546617, 2010). "Four proteins were shown to have increased levels in ovarian cancer serum by both proteomic methods: haptoglobin, alpha-1 antichymotrypsin, serum amyloid P-component, and LRG1." (PMID 20546617, 2010). "Recently, there are several reports in the literature showing increased expression of haptoglobin in ovarian cancer, prostatic carcinoma and pancreatic cancer, and the level of haptoglobin alpha chain up-regulated in serum of breast cancer." (PMID 19785722, 2009).
ovarian carcinoma (continued). "Recently, correlation between haptoglobin, CA 125 and interleukin-6 have been shown in ovarian cancer." (PMID 15199385, 2004). "Some studies have shown increased fucosylation and other carbohydrate changes in serum haptoglobin of ovarian cancer patients." (PMID 15199385, 2004). "Elevated concentrations of serum haptoglobin were reported in ovarian cancer patients in the early seventies." (PMID 15199385, 2004). "The identity of HAP1 was further confirmed by 2-DE Western blotting on the serum from healthy volunteers and grade 1 and 3 ovarian cancer patients using monoclonal anti-human haptoglobin antibody that binds to an epitope within HAP1." (PMID 15199385, 2004). "With this method, the increased fucosylation on haptoglobin was confirmed, particularly in early-stage ovarian cancer compared with normal or benign cases, while the sialylated expressions of haptoglobin and IgG, as well as fucosylated expressions of IgG, displayed no remarkable alterations." (PMID 34485140, 2021). "In concordance, the inflammation marker haptoglobin in the sera of 289 ovarian cancer patients from the AMORIS cohort showed a negative association with survival." (PMID 31069161, 2019). "The results here with Haptoglobin (HP) in Ovarian Cancer agree with previous results." (PMID 30598658, 2018). "In addition to the changes in glycosylation, elevation of the haptoglobin protein levels in the serum and ascitic fluid of ovarian cancer patients has been reported in previous studies." (PMID 22856521, 2012). "In addition to the iTRAQ® data presented here, we have also shown by DIGE analysis that several haptoglobin subunits are present at elevated levels in ovarian cancer sera." (PMID 20546617, 2010). "Still, there are some limitations within the study, mainly because the number of analyzed samples does not allow setting haptoglobin, in a definitive way, as a specific biomarker for ovarian cancer or its early detection, because it would be necessary to analyze samples from stages I and II." (PMID 24576319, 2014). "Moreover, haptoglobin has been reported as a potential serum biomarker of ovarian cancers, 29,30." (PMID 20556197, 2009). "The haptoglobin is one of the richest glycoproteins secreted by the liver, it is reasonable to hypothesize that enhanced hepatic synthesis of the protein will occur due to an acute phase response in ovarian cancer patients resulting in elevated serum haptoglobin precursor concentration." (PMID 31315664, 2019). "The common acute phase proteins HP, HPR, HPX, and SERPINA all showed significant increases with ovarian cancer." (PMID 30598658, 2018). "Peptides and/or phosphopeptides of common plasma proteins such as HPR, HP, HPX, and SERPINA1 showed increased observation frequency and/or precursor intensity in ovarian cancer." (PMID 30598658, 2018). "We selected haptoglobin and PON1, based on the implication of their glycosylation, in particular the sialylation aberration in ovarian cancer and other cancers." (PMID 22856521, 2012). "As haptoglobin is among the most abundant glycoproteins secreted by the liver, it is reasonable to hypothesise that enhanced hepatic synthesis of the protein will occur due to an acute phase response in ovarian cancer patients resulting in elevated serum haptoglobin precursor concentration." (PMID 15199385, 2004). "In agreement with the literature, peptides from many common proteins including acute phase response proteins such as Haptoglobin (HP), Haptoglobin Related Protein (HPR), Alpha Anti Trypsin (SERPINA1) and others were more frequently observed in ovarian cancer samples." (PMID 30598658, 2018). "These integrated results strongly suggest that haptoglobin, PON1 and zinc-alpha-2-glycoprotein may undergo specific sialylation changes at the glycoeptide level in ovarian cancer." (PMID 22856521, 2012).